SMYD3 (SET and MYND domain containing 3)
Diseases named in the same sentence as SMYD3 in open-access papers (continued):
Sharing a sentence is not in itself a finding about the gene and the disease.
pancreatic cancer (12 papers, 2010 to 2023). "In lung and pancreatic cancers, SMYD3 appeared to remain in the cell cytoplasm, where it functioned with the substrate MAP3K2 to enhance signaling through KRas to Erk1/2." (PMID 36838987, 2023). "For example, the abundance of methyltransferase SMYD3 in normal human tissues is low, while it is highly expressed in liver cancer, lung cancer, and pancreatic cancer." (PMID 37220590, 2023). "In lung and pancreatic cancers, SMYD3 is localized in the cytoplasm, where it enhances RAS/ERK signaling by mediating the methylation of MAP3K2 kinase and preventing its interaction with the PP2A phosphatase complex." (PMID 37237385, 2023). "Overexpression of SMYD3 promotes the proliferation, migration, and invasion of pancreatic cancer and acts as a regulator in the cytoplasm by modulating Ras/ERK signaling." (PMID 37220590, 2023). "From this, the authors determined that SMYD3 is necessary for pancreatic cancer initiation via the K-Ras pathway." (PMID 33637115, 2021). "In lung and pancreatic cancers, SMYD3 localization is exclusive to the cytoplasm and it potentiates RAS/ERK signaling through the methylation of the MAP3K2 kinase, by preventing its interaction with a negative regulator, namely the PP2A phosphatase complex." (PMID 31935919, 2020). "Active Src is complexed with and phosphorylates p300 in the nucleus, and the complex is bound to HMGA2 and SMYD3 genes, thereby regulating their expression to promote pancreatic tumor cell migration and invasiveness." (PMID 26695438, 2016). "Functional validations of our results were performed with knockdown of the SMYD3 gene in pancreatic cancer cell lines." (PMID 20525348, 2010). "To confirm results obtained from the association study, we also performed specific siRNA knockdown of the SMYD3 gene in human MIApaca-2 pancreatic cancer cells, followed by cytotoxicity studies." (PMID 20525348, 2010). "Down regulation of SMYD3 mRNA by siRNA desensitized the pancreatic cancer cells to AraC (P-value= 0.0011) when compared with cells transfected with negative control siRNA, a directional change consistent with the results of our CNV association study." (PMID 20525348, 2010). "Notably, SMYD3 was also identified as a signature gene in metastatic pancreatic cancer cells." (PMID 31935919, 2020). "In summary, SMYD3 is critical for the activation of MAP3K2, a key kinase in the Ras-activated MAP signaling pathway, in both lung and pancreatic cancers." (PMID 33637115, 2021). "More importantly, in vivo studies of SMYD3 knockout mice suggest that the enzyme is involved in KRAS driven lung and pancreatic cancer development and in the early stages of liver and colon carcinogenesis." (PMID 29856759, 2018). "Interestingly, SMYD3 knockdown by RNAi has been reported to affect cell proliferation in HCC, BrCA, cervical cancer, EC, CRC, lung adenocarcinoma and KRAS-driven pancreatic cancer cell lines." (PMID 31935919, 2020).
esophageal squamous cell carcinoma (9 papers, 2016 to 2023). Esophageal squamous cell carcinoma (ESCC) is a type of esophageal carcinoma (EC) that can affect any part of the esophagus, but is usually located in the upper or middle third. "Moreover, increased expression of SMYD3 has been found in esophageal squamous cell carcinoma, where it is associated with lymph node metastasis and poor overall survival." (PMID 34503239, 2021). "Furthermore, in HCC and esophageal squamous cell carcinoma, SMYD3 overexpression was associated with the expression of retinoblastoma protein-interacting zinc finger 1 (RIZ1), which has a role in the G2/M checkpoint and is downregulated in several types of human cancers." (PMID 34503239, 2021). "According to the Oncomine database, SMYD3 is also overexpressed in esophageal squamous cell carcinoma, oral cavity squamous cell carcinoma, acute myeloid leukemia, pancreatic ductal adenocarcinoma, leiomyosarcoma and renal Wilms' tumor." (PMID 27626683, 2016). "Interestingly, SMYD3 over-expression in HCC and esophageal squamous cells carcinoma (ESCC) was associated with RIZ1 hypermethylation and mRNA down regulation." (PMID 31935919, 2020). "Expression of SMYD3 is elevated in various cancers, including esophageal squamous cell carcinoma (ESCC), and is correlated with the survival time of patients with ESCC." (PMID 28781952, 2017). "For example, the interaction of lncRNA EZR-AS1 with SMYD3 has been shown to enhance SMYD3-dependent histone H3 lysine 4 (H3K4) methylation and activate EZR transcription in esophageal squamous cell carcinoma (ESCC)." (PMID 31665700, 2019).
lung adenocarcinoma (8 papers, 2016 to 2023). A carcinoma that arises from the lung and is characterized by the presence of malignant glandular epithelial cells. "In a lung adenocarcinoma Kras mutant mouse model, they demonstrated that Smyd3-deficient mice had significantly smaller and less advanced tumors that controls." (PMID 33637115, 2021). "Moreover, in mouse models of Ras-induced lung adenocarcinoma, loss of SMYD3 augments the effectiveness of trametinib in blocking tumorigenesis, highlighting the possibility of combined therapies that may evade resistance." (PMID 37976356, 2023). "In previous work, we identified a specific mechanism in which the SMYD3-mediated methylation of MAP3K2 potentiates the oncogenic KRAS-driven pathway in lung adenocarcinomas." (PMID 35819319, 2022). "Furthermore, SMYD3 has been previously linked to cancer resistance to chemotherapy, and we previously showed that SMYD3 inhibition can potentiate the efficacy of a MEK inhibitor in the context of RAS-induced lung adenocarcinoma." (PMID 35819319, 2022). "We previously identified an oncogenic activity of SMYD3 mediated by MAP3K2 methylation, promoting KRAS-driven lung adenocarcinoma tumorigenesis through ERK1/2 oncogenic activation." (PMID 35819319, 2022). "At most, the gene expression of a histone lysine methyltransferase, SMYD3, and a histone acetyltransferase, HAT1, was considerably increased among 21 and 11 lung adenocarcinoma cell lines, respectively." (PMID 27042856, 2016). "Therefore, the combination of SMYD3 and MLL2 could explain the high specificity of H3K4me3 histone modification to lung adenocarcinoma." (PMID 27042856, 2016). "Since they target different substrates, it is unlikely that these two distinct enzymes would compensate for each other, but the dual inactivation of SMYD2 and SMYD3 may inhibit PDAC (and lung adenocarcinoma) more potently than the inactivation of each enzyme alone." (PMID 26988419, 2016).
bladder cancer (7 papers, 2020 to 2024). "SMYD3 depletion inhibited cell proliferation and colony formation, invasion, and migration in bladder cancer cell lines, as well as xenograft tumor formation in vivo." (PMID 33637115, 2021). "Lastly, BCLAF1 was shown to activate autophagy in bladder cancer cells, underscoring that SMYD3 plays a critical role in bladder cancer oncogenesis and autophagy activation via H3K4me2/me3-mediated regulation of BCLAF1." (PMID 33637115, 2021). "In summary, SMYD3 plays critical roles in bladder cancer oncogenesis, such as interactions with IGF-1R and AKT/mTOR in a possible feedback pathway, cell cycle and apoptotic regulation, and autophagy activation via BCLAF1 regulation." (PMID 33637115, 2021). "First, SMYD3 expression was higher in bladder cancer samples compared to normal matched tissues, and it positively correlated with tumor stage and lymph node metastasis." (PMID 33637115, 2021). "The authors first demonstrated that SMYD3 expression was higher in bladder cancer cell lines than a normal bladder cell line." (PMID 33637115, 2021). "They subsequently showed that SMYD3-depleted bladder cancer cells have decreased H3K4me2 and H3K4me3 expression levels without a significant change in H3K4me1 expression relative to controls." (PMID 33637115, 2021). "The authors also showed that ectopic expression of SMYD3 promotes cell proliferation and invasion in a human bladder cancer cell line." (PMID 33637115, 2021). "Additionally, it has been shown that the up-regulation of histone methyl transferase SMYD3 promotes bladder cancer progression." (PMID 32781788, 2020). "SMYD3 may represent a possible therapeutic target in the treatment of bladder cancer." (PMID 33637115, 2021). "For example, NF-κB and histone methyltransferase SET and MYND domain-containing protein 3 (SMYD3) were reported to be directly involved in the transcriptional regulation of BCLAF1 in diffuse large B cell lymphoma and bladder cancer, respectively." (PMID 38340178, 2024). "It is worth noting that, although the authors demonstrated that SMYD3 physically interacted with the BCLAF1 promoter, it is possible that SMYD3 may regulate bladder cancer growth via AR, because of its previously reported interaction with the receptor." (PMID 32781788, 2020).
lung carcinoma (7 papers, 2018 to 2024). "Further, we illustrate the ability of inhibitors targeting the SET domain of SMYD3 to reduce the viability of colorectal and lung carcinoma cells." (PMID 35076487, 2021). "The overexpression of SMYD3 has been discovered in several cancer types, including breast, colorectal, and lung carcinomas." (PMID 35076487, 2021). "We studied the effects of EPZ028862 in a panel of KRAS mutant lung cancer cell lines including A549, for which RNAi-based knockdown studies had previously suggested an important role for SMYD3 in proliferation." (PMID 29856759, 2018). "In lung cancers and PCs, SMYD3 has a pivotal role in the regulation of oncogenic RAS signaling through the methylation of MAP3K2 kinase on lysine 206, which induces MAP3K2 release from the negative regulator PP2A phosphatase complex and therefore promotes ERK1/2 phosphoactivation." (PMID 34503239, 2021). "Other HMTs, such as SET domain containing 8 (SETD8), SET and MYND domain containing 3 (SMYD3), SETDB1, and PRMT5, are also overexpressed in lung cancer, correlating with the tumor’s aggressiveness and clinical characteristics." (PMID 38525426, 2024).
pancreatic ductal adenocarcinoma (7 papers, 2016 to 2023). An infiltrating adenocarcinoma that arises from the epithelial cells of the pancreas. "Ras-driven carcinomas and their connection to enhanced expression of SMYD3 have been studied in pancreatic ductal adenocarcinomas in which aberrantly expressed SMYD3 plays a key role in tumorigenesis." (PMID 36838987, 2023). "Moreover, analyses of human pancreatic ductal adenocarcinoma (PDAC) tumor tissues detected the association of nuclear Src with the HMGA2 and SMYD3 gene promoters." (PMID 26695438, 2016). "In pancreatic ductal adenocarcinoma, S100A11 bound to SMYD3 and then activated the expression of transketolase (TKT), thus stimulating pentose phosphate pathway to aggregate the malignant phenotypes." (PMID 37386026, 2023). "In a previous work, we characterized the first clearly defined mechanism of SMYD3 oncogenic activity in KRAS-induced lung and pancreatic ductal adenocarcinoma." (PMID 35819319, 2022).
lymph node metastasis (5 papers, 2018 to 2023). "Increased SMYD3 expression was associated with lymph node metastasis and was an independent prognostic factor of poor overall survival." (PMID 33637115, 2021). "Specifically, SMYD3 promoter methylation is significantly decreased in patients with lymph node metastasis and stage III/IV disease." (PMID 36816359, 2023). "First, they found that SMYD3 expression correlated with lymph node metastasis and shorter overall survival." (PMID 33637115, 2021). "The level of SMYD3 expression was positively correlated with tumor stage and lymph node metastasis." (PMID 32007952, 2020). "SMYD3 showed clinical significance and was related to tumor stage, lymph node metastasis, and the presence or absence of periodontitis." (PMID 33542221, 2021).
renal cell carcinoma (5 papers, 2021 to 2025). "Depletion of SMYD3 leads to an inhibition of renal cell carcinoma (RCC) cell proliferation, and HIF-2α can directly bind to the SMYD3 promoter in order to stimulate SMYD3 transcription and expression." (PMID 33637686, 2021). "Thus, EGFR activation mediated by the VHL/HIF-2α/SMYD3 signaling cascade promotes renal cell carcinoma progression." (PMID 39482529, 2024). "Another study revealed SMYD3 as a mediator between the von Hippel‒Lindau/hypoxia-inducible factor α (VHL-HIFα) axis and epidermal growth factor receptor (EGFR) in renal cell carcinoma." (PMID 39482529, 2024).
diffuse large B-cell lymphoma (4 papers, 2022 to 2024). "Another piece of evidence corroborating the implication of SMYD3 in cancer metabolism was that SMYD3 increased pyruvate kinase M2 (PKM2) expression to support a hyperproliferative phenotype in diffuse large B-cell lymphoma (DLBCL)." (PMID 37386026, 2023). "In diffuse large B-cell lymphoma (DLBCL), SMYD3 bound specific sequences of PKM2 and promoted DLBCL cell proliferation and aerobic glycolysis via H3K4me3-mediated PKM2 transcription." (PMID 37237385, 2023).
autosomal dominant polycystic kidney disease (3 papers, 2022 to 2024). Autosomal dominant form of polycystic kidney disease. "Additionally, SMYD3 may contribute to autosomal dominant polycystic kidney disease and renal carcinoma via its lysine methyltransferase activity." (PMID 36250097, 2022). "Mutations in polycystin 2 are known to cause ADPKD (autosomal dominant polycystic kidney disease), suggesting that SMYD3 may contribute to cyst growth in ADPKD in a cilia-dependent manner." (PMID 38892227, 2024).
chronic lymphocytic leukemia (3 papers, 2019 to 2024). "In chronic lymphocytic leukemia (CLL) cells, STAT3 is directly associated with the SMYD3 promoter and favors SMYD3-mediated cell growth both in vivo and in vitro." (PMID 31935919, 2020). "Similarly, SMYD3 is directly regulated by STAT3 in chronic lymphocytic leukemia." (PMID 39482529, 2024). "Similarly, in chronic lymphocytic leukemia (CLL) patients, SMYD2 and SMYD3 are overexpressed, accompanied by a high white blood cell count and complex karyotype." (PMID 31370883, 2019).
endometrial carcinoma (3 papers, 2024). A malignant tumor arising from the epithelium that lines the cavity of the uterine body. "Despite the well-established association of histone methyltransferase SMYD3 with the development and progression of various cancers, its specific oncogenic role in endometrial cancer remains unexplored." (PMID 38191478, 2024). "In detail, we provide evidence that SMYD3 expression is upregulated in endometrial cancer and associated with EC progression." (PMID 38191478, 2024). "Pathway analysis identifies a close association between SMYD3 and the DNA repair pathway in endometrial cancer." (PMID 38191478, 2024). "In endometrial carcinoma, the mutation frequencies were 3.3% for SMYD1, 2.1% for SMYD2, 2.1% for SMYD3, 2.1% for SMYD4, and 2.4% for SMYD5." (PMID 38892284, 2024). "The expression of Smyd3 in mouse endometrial carcinoma was significantly upregulated compared with that in normal uterus." (PMID 38191478, 2024). "In conclusion, this study unveils a novel mechanism by which SMYD3 contributes to endometrial cancer, shedding light on its dynamic regulation of the LIG4/XRCC4/XLF complex in the NHEJ pathway." (PMID 38191478, 2024). "Immunohistochemistry (IHC) staining of human endometrial cancer tissues across various pathological categories further underscored the significant upregulation of SMYD3 in different EC subtypes." (PMID 38191478, 2024). "To assess the role of SMYD3 in endometrial cancer, we first collected fresh paired samples from patients with EC." (PMID 38191478, 2024). "Knockdown of SMYD3 inhibits the proliferation, migration, and invasion abilities of endometrial cancer cells in vivo and in vitro." (PMID 38191478, 2024). "Despite these substantial findings across various tumor types, the specific role of SMYD3 in endometrial cancer remains elusive and has yet to be elucidated." (PMID 38191478, 2024). "More importantly, the inhibition of SMYD3 with its specific inhibitor BCI-121 significantly sensitized endometrial cancer cells to radiotherapy." (PMID 38191478, 2024). "In summary, these findings are consistent with the in vitro results, indicating that SMYD3 promotes endometrial cancer growth and metastasis in vivo." (PMID 38191478, 2024). "The observations above prompted us to explore the potential biological function of SMYD3 in endometrial cancer progression." (PMID 38191478, 2024). "To further establish the clinical significance of heightened SMYD3 expression, we examined endometrial cancer tissue microarrays, revealing a clear correlation between SMYD3 expression levels and EC clinical grade." (PMID 38191478, 2024). "Targeting SMYD3, particularly in combination with radio/chemotherapy, emerges as a promising strategy for anticancer therapy in endometrial cancer." (PMID 38191478, 2024). "In this study, we report for the first time that SMYD3 plays a significant role in endometrial cancer progression, and we identified a novel mechanism of SMYD3-mediated NHEJ repair in endometrial cancer." (PMID 38191478, 2024). "Our study extends this understanding to endometrial cancer, demonstrating that the knockdown of SMYD3 hinders cell proliferation, migration, and invasion abilities in EC cells." (PMID 38191478, 2024). "Importantly, we provide evidence that the oncogenic properties of SMYD3 in endometrial cancer depend on its methyltransferase activity, as demonstrated by using an enzymatically inactive SMYD3-F183A plasmid." (PMID 38191478, 2024). "Altogether, these findings indicate that SMYD3 contributes to endometrial cancer progression." (PMID 38191478, 2024). "Overall, these findings suggest that SMYD3 could indeed serve as a potential therapeutic target in endometrial cancer, offering insights into a promising treatment strategy." (PMID 38191478, 2024). "Moreover, we examined the impact of SMYD3 on liver metastasis by implanting the spleens of mice, following a paradigm established in previous endometrial cancer studies." (PMID 38191478, 2024).
endometrial carcinoma (continued). "Our results suggest that SMYD3 might be a promising therapeutic target for endometrial cancer." (PMID 38191478, 2024). "Collectively, our comprehensive data position SMYD3 as a central factor in NHEJ repair and underscore its potential as a promising pharmacological target for endometrial cancer therapy, validated through both in vitro and in vivo systems." (PMID 38191478, 2024). "Both in vitro and in vivo experiments have shown that SMYD3 depletion in endometrial cancer reduces cell proliferation and compromises nonhomologous end joining (NHEJ) repair." (PMID 39482529, 2024). "Moreover, the SMYD3 inhibitor BCI-121, which is utilized to treat endometrial cancer, attenuates the tumorigenicity of endometrial cancer and improves the efficacy of radiotherapy." (PMID 39482529, 2024). "However, whether SMYD3 is involved in NHEJ repair and participates in endometrial cancer development remains unknown." (PMID 38191478, 2024).
metastatic tumor (3 papers, 2023 to 2025). "Collectively, SMYD3 is upregulated at both transcript and protein levels in CRC, associates with metastatic disease, and independently predicts poor survival." (PMID 41301830, 2025). "Further stratification of TCGA-COAD cases showed that tumors with distant metastasis (M1, n = 52) exhibited markedly higher SMYD3 expression than both non-metastatic tumors (M0, n = 333) and normal controls (n = 820)." (PMID 41301830, 2025). "This implies that pharmacological inhibition of SMYD3 activity provides an additional mechanism for disrupting the Ras/MAPK signaling axis that may be critical in metastatic disease, particularly CRPC." (PMID 37976356, 2023). "Moreover, we showed that SMYD3 stable knock-out or pharmacological inhibition drastically decreases CRC tumorigenicity in vivo and reduces the metastatic potential of CRC-SCs, indicating that SMYD3 is involved in primary tumor initiation and metastatic tumor dissemination." (PMID 40588481, 2025).